ZAP70 (zeta chain of T cell receptor associated protein kinase 70)
Description:
Tyrosine kinase that plays an essential role in regulation of the adaptive immune response. Regulates motility, adhesion and cytokine expression of mature T-cells, as well as thymocyte development. Also contributes to the development and activation of primary B-lymphocytes. When antigen presenting cells (APC) activate T-cell receptor (TCR), a serie of phosphorylations lead to the recruitment of ZAP70 to the phosphorylated TCR components CD3E and CD247/CD3Z through ITAM motif at the plasma membrane. This recruitment serves to localization to the stimulated TCR and to relieve its autoinhibited conformation. Release of ZAP70 active conformation is further stabilized by phosphorylation mediated by LCK. Subsequently, ZAP70 phosphorylates at least 2 essential adapter proteins: LAT and LCP2. In turn, a large number of signaling molecules are recruited and ultimately lead to lymphokine production, T-cell proliferation and differentiation. Furthermore, ZAP70 controls cytoskeleton modifications, adhesion and mobility of T-lymphocytes, thus ensuring correct delivery of effectors to the APC. ZAP70 is also required for TCR-CD247/CD3Z internalization and degradation through interaction with the E3 ubiquitin-protein ligase CBL and adapter proteins SLA and SLA2. Thus, ZAP70 regulates both T-cell activation switch on and switch off by modulating TCR expression at the T-cell surface. During thymocyte development, ZAP70 promotes survival and cell-cycle progression of developing thymocytes before positive selection (when cells are still CD4/CD8 double negative). Additionally, ZAP70-dependent signaling pathway may also contribute to primary B-cells formation and activation through B-cell receptor (BCR).
Synonyms: SRK; ZAP-70; STD; ADMIO2; IMD48; STCD; TZK
Tractability: Small molecule: a structure with a bound ligand is known; a high-quality ligand is known; it has a high-quality binding pocket; it belongs to a druggable protein family. Antibody: UniProt places it where antibodies can reach, with high confidence; its Gene Ontology location is reachable by antibodies, with high confidence. PROTAC: UniProt records ubiquitination sites on it; ubiquitination databases record sites on it; its protein half-life has been measured; a small molecule that binds it is known.
Target class: Tyrosine protein kinase Syk family; TK protein kinase group; Enzyme; Protein Kinase; Kinase
Safety:
Unwanted effects reported when the protein is acted on. In parentheses: how it was acted on, where the effect was seen, and who reports it.
cardiac arrhythmia (cardiovascular system; source: Lamore et al. (2017))
Gene: Protein-coding gene on chromosome 2 (97,713,576 to 97,744,327, forward strand). Ensembl gene ENSG00000115085.
Subcellular location: Cytoplasm; Cell membrane
Pathways (Reactome):
Immune System: Generation of second messenger molecules; Translocation of ZAP-70 to Immunological synapse
Disease: Nuclear events stimulated by ALK signaling in cancer
Signal Transduction: RHOH GTPase cycle
Gene Ontology:
Molecular function: non-membrane spanning protein tyrosine kinase activity; protein binding; protein tyrosine kinase activity; ATP binding; phosphotyrosine residue binding; protein kinase activity
Biological process: immune response; peptidyl-tyrosine phosphorylation; positive regulation of T cell differentiation; positive thymic T cell selection; protein phosphorylation; T cell activation; T cell receptor signaling pathway; adaptive immune response; B cell activation; intracellular signal transduction; T cell aggregation; T cell differentiation; T cell migration; leukocyte cell-cell adhesion; leukocyte migration
Cellular component: cytoplasm; membrane raft; plasma membrane; T cell receptor complex; cytosol; cell-cell junction; immunological synapse; membrane
Genetic constraint (gnomAD): Loss-of-function variants: 29 observed, 63.37 expected, observed/expected ratio (o/e) 0.46, 90% interval 0.34 to 0.62. The upper end of that interval is the gene's LOEUF score, 0.62, which puts it in group 2 of 6, group 1 being the genes least tolerant of losing a copy. Missense variants: 696 observed, 842.1 expected, observed/expected ratio (o/e) 0.83, 90% interval 0.78 to 0.88. Synonymous variants: 363 observed, 348.4 expected, observed/expected ratio (o/e) 1.04, 90% interval 0.95 to 1.14.
Gene-disease validity (ClinGen):
ClinGen rates the evidence that ZAP70 causes each of these diseases.
combined immunodeficiency due to ZAP70 deficiency (autosomal recessive): Definitive. Combined immunodeficiency due to ZAP70 deficiency is a very rare, severe, genetic, combined immunodeficiency disorder characterized by lymphocytosis, decreased peripheral CD8+ T-cells, and presence of normal circulating CD4+ T-cells, leading to immune dysfunction.
Homologues: Orthologues: chimpanzee ZAP70 (99% identical), macaque ZAP70 (98% identical), rabbit ZAP70 (95% identical), mouse Zap70 (94% identical), rat Zap70 (92% identical), dog ZAP70 (92% identical), guinea pig ZAP70 (78% identical), tropical clawed frog zap70 (72% identical), zebrafish zap70 (64% identical). Paralogues in human: SYK (55% identical), ABL2 (28% identical), ABL1 (27% identical), LCK (27% identical), SRC (27% identical), FYN (27% identical), BLK (26% identical), PTK2 (26% identical), YES1 (26% identical), HCK (26% identical), LYN (26% identical), JAK3 (25% identical), and 20 more.
Diseases named in the same sentence as ZAP70 in open-access papers:
ZAP70 is named in the same sentence as 150 diseases in open-access papers, as found by Europe PMC text mining. Sharing a sentence is not in itself a finding about the gene and the disease. The quoted sentences say what the papers report.
chronic lymphocytic leukemia (57 papers, 2008 to 2026). "Consistent with this, the ZAP70 gene has been clearly implicated in the development of chronic lymphocytic leukaemia." (PMID 41174288, 2026). "This elevated DDR1 expression is significantly associated with the ZAP70 gene, which is a well-known prognostic marker in chronic lymphocytic leukemia." (PMID 37627077, 2023). "ZAP70 has been reported to have a significant association with poor overall survival in chronic lymphocytic leukaemia." (PMID 36299526, 2022). "Aberrant expression of ZAP-70 has been evidenced in different B cell malignancies, with high expression of ZAP-70 in a subset of patients with Chronic Lymphocytic Leukemia (CLL), associating with unfavorable disease outcomes." (PMID 33194762, 2020). "ZAP-70 in chronic lymphocytic leukemia (CLL) is associated with enhanced response to microenvironmental stimuli." (PMID 24312539, 2013). "Zeta-chain-associated protein kinase 70 (ZAP-70), expressed in patients with aggressive chronic lymphocytic leukemia (CLL) and required for cell survival and signaling in CLL, behaves as an Hsp90 client protein only in CLL cells." (PMID 19090995, 2008). "Among these genes, ZAP70 encodes a kinase essential for thymopoiesis, T‐cell receptor‐dependent survival, and proliferation and is aberrantly expressed in B‐cell malignancies, such as acute lymphoblastic leukemia and chronic lymphocytic leukemia." (PMID 29575763, 2018). "Successful examples of this approach include identifyingsubtypes of diffuse large B-cell lymphomas with different prognoses and increasedexpression of the zeta-chain (TCR) associated 70 kDa protein kinase(ZAP70) in chronic lymphocytic leukemia (CLL) which is apredictor of the clinical course." (PMID 21359205, 2011). "In chronic lymphocytic leukemia (CLL), the expression of zeta-chain-associated protein kinase-70 (ZAP-70) is a significant component in the development of a poor prognosis of the disease." (PMID 37446908, 2023). "ZAP70 in B-cell lymphocytic leukemia cells correlated with the expression in NK cells represents a surrogate biomarker for mutation status." (PMID 35477402, 2022). "ZAP70 up-regulation enhanced chemokine-induced chronic lymphocytic leukemia cellular migration and arrest through valency regulating integrins." (PMID 35477402, 2022). "Chronic lymphocytic leukemia (B-CLL) aberrantly expresses ZAP-70, remodels the Syk-mediated BCR downstream signaling." (PMID 35260878, 2022). "In the early 2000s, the aberrant high expression of ZAP-70 was identified in a subset of Chronic Lymphocytic Leukemia (CLL) patients, which turned out to also reflect an unfavorable clinical outcome." (PMID 33194762, 2020). "Under physiologic conditions ZAP-70 is expressed by T cells and NK cells, however in chronic lymphocytic leukemia (CLL) and B cell acute lymphoblastic leukemia (B-ALL) it was found in a subset of B cells, as well." (PMID 31137740, 2019). "Cortactin is upregulated in several cancers to trigger cell migration and invasiveness, and both cortactin and HS1 are related to poor prognosis in adult B-cell chronic lymphocytic leukemia (B-CLL), and linked to high levels of the known risk factors ZAP70 and CD38." (PMID 30573781, 2019). "Remarkably, we recently identified ZAP70, which is aberrantly expressed in chronic lymphatic leukemia (CLL), to enhance chemokine-driven CLL arrest by promoting integrin clustering." (PMID 30692994, 2018). "In chronic lymphatic leukemia, a single CpG dinucleotide has been identified to be important for ZAP-70 expression and prognosis." (PMID 29610526, 2018). "Hypermethylation of ZAP70 gene predicted an unfavorable disease course in terms of disease progression and overall survival in chronic lymphocytic leukemia." (PMID 28814981, 2017). "In chronic lymphocytic leukemia DNA methylation of a single CpG in the promoter of ZAP-70 predicts the outcome." (PMID 27880937, 2016).
chronic lymphocytic leukemia (continued). "FC can also be used to identify the expression of targets for potential antibody-directed therapy and provide additional prognostic information such as CD38 and ZAP-70 expression in chronic lymphocytic leukemia/small lymphocytic lymphoma (CLL/SLL)." (PMID 27725920, 2016). "Recently, A6 has been shown to be directly cytotoxic for B-lymphocytes obtained from patients with chronic lymphocytic leukemia expressing the kinase, ZAP-70." (PMID 25870596, 2015). "We showed higher expression of CD74 in CLL and its correlation with known prognostic factor ZAP70 and stage of the disease in chronic lymphocytic leukemia." (PMID 23572149, 2013). "Using microarray based gene expression profiling we have recently demonstrated that the gene for Pgrn, granulin (GRN), is significantly higher expressed in aggressive CD38+ZAP-70+ as compared to indolent CD38−ZAP-70− chronic lymphocytic leukemia (CLL) cases." (PMID 24009671, 2013). "Compared to protein-based analysis, the DNA methylation status of ZAP-70 provides more accurate prognostic information for chronic lymphocytic leukemia." (PMID 24345474, 2013). "Previously we found that TAPP2 was predominantly expressed in a more clinically aggressive ZAP-70+ subset of chronic lymphocytic leukemia (CLL) B cells, known to be highly migratory in nature." (PMID 23460911, 2013). "In liver cancer, the hypermethylation of one CpG silenced transcriptional expression of TTP and, in chronic lymphatic leukemia, a single CpG dinucleotide has been identified to be important for ZAP-70 expression and prognosis." (PMID 24260468, 2013). "One major goal is to find candidate genes that can become targets for epigenetic treatment or act as prognostic markers (e.g. ZAP70 in chronic lymphocytic leukemia), to be able to accurately predict treatment responses." (PMID 24367530, 2013). "Additional studies have found that ZAP-70 has functional significance in chronic lymphocytic leukemia." (PMID 31803286, 2012). "Moreover, RG7356 induced rapid internalisation of CD44 in chronic lymphocytic leukaemia cells expressing the zeta-associated protein of 70 kDa (ZAP-70), resulting in ZAP-70 inhibition and subsequently promoting caspase-dependent apoptosis." (PMID 34944493, 2021). "In one of the early studies conducted using microarray profiling, a 13-miRNA signature distinguished (i) chronic lymphocytic patients exhibiting high expression of ZAP-70 (prognostic factor) from patients with low levels of ZAP-70 and (ii) between cases with mutated and unmutated IgVH." (PMID 29854719, 2018). "ZAP70 gene expression is associated with poor prognosis in B-cell lymphoproliferative disorders especially chronic lymphocytic leukaemia (CLL) but its role in adult B-ALL has not been established." (PMID 22548957, 2012). "Studies examined biopsies and serum samples from patients with B-cell chronic lymphocytic leukemia (CLL) and found that the levels of IL-9 mRNA and protein expression were altered and correlated with Rai staging, ZAP70, and CD38." (PMID 37048814, 2023). "Finally, an intron variant of ZAP70 (rs7425883) is associated with a decreased risk of developing non-Hodgkin lymphoma, and aberrant elevated expression of ZAP70 in B cell CLL cells correlates with enhanced BCR signaling in the leukemic cells and poorer prognosis." (PMID 34012443, 2021). "Chronic lymphocytic leukemia (CLL) is a disease that shows varying clinical progression, and expression of the protein tyrosine kinase ZAP70 has been described as a very valuable prognostic factor." (PMID 26376785, 2016). "For example, in chronic lymphocytic leukemia (CLL), ZAP-70+ lymphocytes express activated HSP90 which binds and stabilizes ZAP-70 with several HSP co-chaperones." (PMID 19183457, 2009). "Despite being absent in normal B cells ZAP-70 functions as an adaptor protein promoting BCR signalling in a subset of chronic lymphocytic leukaemia (CLL), where its presence confers inferior clinical outcomes." (PMID 35077445, 2022).
chronic lymphocytic leukemia (continued). "Moreover, MELK overexpression was also found in chronic lymphocytic leukemia (CLL) cells, and positively correlated with advanced stage, higher WBC count, increased β2-MG level, elevated LDH, unmutated IGHV, deletion of 17p13, positive ZAP-70 and inferior prognosis of CLL patients." (PMID 32047721, 2020). "In chronic lymphocytic leukemia (CLL), the pattern of sno/scaRNAs expression is unrelated to the major biological (ZAP-70 and CD38), molecular (immunoglobulin heavy chain gene mutation), and cytogenetic markers." (PMID 32916783, 2020). "ZAP-70 is an independent negative prognostic marker in chronic lymphocytic leukemia (CLL)." (PMID 20211015, 2010). "His medical history included a papillary thyroid cancer treated with radiation therapy 8 years prior, untreated chronic lymphocytic leukemia (Rai stage 0; 13q, CD38, and ZAP-70 negative) 17 years prior, and a current prostate-specific antigen (PSA) value of 9 ng/ml (normal <4 ng/ml)." (PMID 38632333, 2024).
Immunodeficiency (34 papers, 2015 to 2025). Failure of the immune system to protect the body adequately from infection, due to the absence or insufficiency of some component process or substance. "ZAP70 variants can cause a range of immunodeficiencies with variable clinical presentations, including infections and malignancies." (PMID 40901120, 2025). "ZAP70 deficiency is typically associated with combined immunodeficiency and rarely with malignancies such as leukemia or lymphoma." (PMID 40901120, 2025). "ZAP70 serves as a critical downstream signaling molecule in T cell activation; its deficiency can result in severe immunodeficiencies." (PMID 39457014, 2024). "One such example is the immunodeficiency due to mutations in the ZAP70 protein tyrosine kinase (PTK) gene, at least during the neonatal period." (PMID 37313400, 2023). "The finding that LAT-deficient patients, like many ZAP-70-deficient patients, present with immunodeficiency as well as autoimmunity raises questions concerning the intricate crosstalk that regulate T cell responses from TCR signaling hubs." (PMID 37313400, 2023). "Deleterious mutations in the SH2-C domain result in attenuated ZAP-70 function and clinical manifestations of immunodeficiency." (PMID 37313400, 2023). "All together, we find that these mutations are pathogenic; defective folding of R170C and R192W ZAP-70 variants results in clinical manifestations of immunodeficiency and autoimmunity." (PMID 37313400, 2023). "The vast majority of ZAP70 mutations that are responsible for a pathological immunodeficiency result in a dramatically reduced TCR-induced signaling in vitro." (PMID 37313400, 2023). "In fact, the majority of mutations in ZAP70 that are associated with immunodeficiency or autoimmunity in human and mice are hypomorphic alleles that result in complete or partial loss of ZAP70 function." (PMID 34923645, 2022). "Of note, a C564 mutation in the tyrosine kinase domain of ZAP70 was previously reported in severe combined immunodeficiencies." (PMID 34742736, 2021). "ZAP70 deficiency results in a spectrum of immune deficiency or dysregulation ranging from atopy, autoimmunity, and late-onset combined immunodeficiency to severe, combined T and B cell deficiency from birth." (PMID 28603521, 2017). "Specifically, loss of ZAP-70 results in severe immunodeficiency associated with impaired T cell maturation in the thymus and their reduced activation in the periphery; at the same time, single-nucleotide substitution of ZAP-70 is associated with autoimmunity." (PMID 38432631, 2024). "Moreover, a homozygous ZAP-70 R192W variant was identified in 2 siblings with combined immunodeficiency and CD8 lymphopenia, confirming the pathogenicity of this mutation." (PMID 37313400, 2023). "The consequence of loss of ZAP70 function is immunodeficiency in both mouse and man." (PMID 34923645, 2022). "Interestingly, similar to the hypomorphic ZAP70 mutations that can lead to immunodeficiency and/or autoimmunity in humans, a second study of LAT mutations presents a more complicated phenotype with some unexpected clinical and immunologic features." (PMID 34923645, 2022). "Loss of Zap70 in both humans and mice results in severe immunodeficiency." (PMID 28415650, 2017). "However, recognizing immune deficiency caused by a loss of function mutation in ZAP70 can be difficult and even delayed because most patients have detectable lymphoid tissue, normal lymphocyte counts and immunoglobulin levels." (PMID 27448562, 2016). "However, the experiments were done on the SKG mice with immunodeficiency due to a mutation of the gene ZAP-70." (PMID 26361229, 2015). "And ZAP70 mutations could cause severe immunodeficiency disease." (PMID 36776357, 2022).